MTOR (mechanistic target of rapamycin kinase)
Diseases named in the same sentence as MTOR in open-access papers (continued):
Sharing a sentence is not in itself a finding about the gene and the disease.
sarcoma (continued). "Finally, we did not consider in our preclinical experiments, the potential impact of the combination of trabectedin and mTOR inhibitors in the sarcoma immune microenvironment." (PMID 38758230, 2024). "Finally, mTOR inhibitors combined with ERK inhibition demonstrated activity against HRASmt G12V-driven autochthonous sarcoma." (PMID 38672653, 2024). "How does blockade of TMG-tgs mRNA prevent sarcoma recovery from mTOR inhibitor?" (PMID 37386121, 2023). "The IGF‐1R/mTOR pathway is frequently activated in sarcomas and other solid tumors, so it is considered an attractive target for Osteosarcoma (OS) and Ewing sarcoma (ES) since it represents the aggregation of multiple chemical and mechanical signaling mechanisms." (PMID 36807772, 2023). "In LEATs, molecular alterations that can be linked to epileptogenesis are found in the Rat sarcoma/mitogen-activated protein kinase/extracellular signal-regulated kinase (RAS/MAPK/ERK) pathway and the phosphoinositide 3-kinase/protein kinase B/mammalian target of rapamycin (PI3K/AKT/mTOR) pathway." (PMID 36289737, 2022). "EWSR1-NFATc2 fusion positive sarcomas are molecularly distinct entities with overactive mTOR signaling; which may be therapeutically targetable." (PMID 34021224, 2021). "Furthermore, we report a clinical case of a patient with an EWSR1-NFATc2 fusion positive sarcoma whose tumor was stabilized by mTOR combination therapy." (PMID 34021224, 2021). "Pathway analysis identified a significant activation of the mTOR pathway in EWSR1-NFATc2 positive sarcomas compared to either EWSR1-ETS or CIC-DUX4 positive sarcomas (EWSR1-NFATc2 vs. EWSR1-ETS: z-score = 1.6, p = 0.002; EWSR1-NFATc2 vs. CIC-DUX4: z-score = 1, p < 0.001)." (PMID 34021224, 2021). "Additionally, we evaluate altered pathways using transcriptomic data and highlight the importance of the mTOR pathway in EWSR1-NFATc2 fusion positive sarcomas." (PMID 34021224, 2021). "Given the suggested activation of mTOR in EWSR1-NFATc2 fusion positive sarcomas, and the conservation of the primary transactivation and regulatory domains of NFATc2 in EWSR1-NFATc2 fusion, we proceeded to assess the role of NFATc2 overexpression on mTOR in a tumor agnostic fashion." (PMID 34021224, 2021). "Given that the AKT/mTOR pathway lies downstream of IGF-1/IGF-1R signaling and the success of combined mTOR/IGF-1R inhibition in sarcomas, future clinical trials could benefit from looking at a similar combined approach to chordoma management." (PMID 32733369, 2020). "Targeting the mTOR pathway to treat sarcomas is already underway." (PMID 30410720, 2018). "Here we present the results of the Phase II portion of a Phase I/II clinical trial that aimed to overcome the chemoresistance of sarcoma CSC by combining the mTOR inhibitor temsirolimus (20 mg/m2 weekly) with the chemotherapeutic agent liposomal doxorubicin (30 mg/m2 monthly)." (PMID 30410720, 2018). "We have shown in preclinical testing that ALDHhigh cells are resistant to chemotherapy agents commonly used to treat sarcomas, such as doxorubicin, and that inhibition of the mTOR pathway with agents such as rapamycin can overcome this chemoresistance seen in the ALDHhigh cells." (PMID 30410720, 2018). "The rationale for this study was our in vitro observation that mTOR inhibition increases the sensitivity of sarcoma stem cells to chemotherapy and our hypothesis that eliminating CSC would translate into improved survival." (PMID 30410720, 2018). "Clinical trials in sarcoma with single agent mTOR inhibitors have shown modest efficacy at best." (PMID 30410720, 2018). "We have previously published the results of the dose finding portion of this study and are reporting here the results of the Phase II portion of the clinical trial, including pharmacodynamic data regarding mTOR inhibition and targeting of ALDHhigh sarcoma cells." (PMID 30410720, 2018).
sarcoma (continued). "Activation of the PI3K/AKT/mTOR pathways through different mechanisms including activation of IGFR or PI3K, loss of PTEN, RICTOR amplification and/or increased p-AKT has been reported in LMS and other sarcoma subtypes." (PMID 26952093, 2016). "Thus, the dephosphorylation of PRAS40 by IS in sarcoma cells in vitro and in vivo, contributed to the disassociation of mTOR-Raptor complex." (PMID 27056897, 2016). "The autophagy inhibitor chloroquine (or HCQ) blocks the process in CAFs and stops the energy flow to sarcoma cells, while the autophagy inducer, Rapa, inhibits mammalian target of rapamycin (mTOR) signaling and induces autophagy in cancer cells to reduce tumor growth rate." (PMID 26375670, 2015). "Several studies have demonstrated the activation of the Akt/mTOR pathway in various sarcomas." (PMID 26502919, 2015). "Thus further understanding of the role of the mTOR pathway in the oncogenesis of sarcomas is warranted." (PMID 24216984, 2013). "Besides monotherapy with mTOR inhibitors, several combinations with other agents including anthracyclines are being investigated in sarcomas." (PMID 23300809, 2012). "Clinical studies of mTOR inhibitors have demonstrated encouraging results across a broad range of tumor types and present promising treatment options, particularly for patients with advanced sarcoma, whose tumors are challenging to treat." (PMID 21837674, 2012). "For instance, in sarcoma, breast and leukemia cancer cells, activation of NFκB by TNFα leads to inhibition of autophagy as a result of mTOR pathway activation, whereas NFκB activation during the recovery period from heat shock has been shown to activate autophagy and promote survival." (PMID 23056618, 2012). "Preclinical studies of rapamycin in mice as well as recent data using novel and approved rapalogs (Ridaforolimus, Ariad; Temsirolimus, Wyeth) in human patients suggest that mTOR blockade may be active in several cancers including sarcoma." (PMID 20543980, 2010). "In addition, considering that CDSs are highly aggressive sarcomas and that Akt/mTOR signaling enhances cancer metastasis, we verified whether combined treatment was effective against CDS metastatic dissemination." (PMID 34903601, 2022). "Our study adds to the literature supporting the addition of mTOR inhibition to chemotherapy agents for the treatment of sarcomas, and proposes that a mechanism by which mTOR inhibition enhances the efficacy of chemotherapy may be through sensitizing the chemoresistant CSC population." (PMID 30410720, 2018). "Interestingly, in a platform screening, mTOR was demonstrated overexpressed in over 2000 sarcomas." (PMID 29156702, 2017). "Thus, inhibition of mTOR also results in an antiangiogenic effect in sarcomas." (PMID 24216984, 2013). "Thus, mTOR inhibitors were a natural choice to test clinically in sarcomas." (PMID 22665999, 2012). "However, the status of mTOR activation of these sarcomas is unknown, although in one study the presence of S6 phosphorylation correlated with a higher likelihood of disease control with an mTOR inhibitor." (PMID 22943457, 2012). "A phase I study combining temsirolimus (mTOR inhibitor) with cixutumumab (IGF-1R antibody) showed tolerability and early efficacy signals in pediatric sarcomas, including RMS." (PMID 40821216, 2025). "This study identifies altered HMGA2/IGF2BP/IGF2 signaling in CIC-DUX4 sarcomas and provides proof of principle for combination therapy with trabectedin and AKT/mTOR dual inhibitors to specifically combat the disease." (PMID 34903601, 2022).
sarcoma (continued). "The phosphorylated protein of p-Akt, p-mTOR, and p-S6 in the adjacent normal tissue and UPS sarcoma tissue from the 68 patients were detected by immunohistochemistry." (PMID 35559021, 2022). "Coincidentally, both mTOR and KLF4 are target genes of hsa-mir-7-5p and hsa-mir-145-5p, and both are also aberrantly highly expressed in sarcoma." (PMID 34696664, 2022). "In the relapsed or refractory setting, multiple agents targeting VEGFR, PDGFR, mechanistic target of rapamycin (mTOR), and IGFR, among others, are being evaluated for pediatric sarcomas." (PMID 34604027, 2021). "Clinical trials in sarcoma with mTOR inhibitors as single agents have shown modest efficacy in STS; however, the combination of mTOR inhibitors and conventional chemotherapy has yielded more promising results." (PMID 32532153, 2020). "The comparison of the DSS values among our sarcoma cohort (14 cases) showed that drug classes such as histone deacetylase (HDAC), cyclin-dependent kinase (CDK), proteasome, mitosis, and mTOR inhibitors were active in most of the sarcoma subtypes tested." (PMID 30745580, 2019). "We screened 19 anticancer compounds, targeting the epidermal growth factor receptor (EGFR), MEK, and PI3K/mTOR on 12 head and neck squamous cell carcinoma (HNSCC) cell lines cultured on plastic, mouse sarcoma–derived Matrigel (MSDM), and Myogel." (PMID 31905951, 2019). "In this study, using a high-throughput drug screening method, we tested 12 HNSCC cell lines cultured on plastic, mouse sarcoma–derived Matrigel, or Myogel using 19 anticancer compounds targeting EGFR, MEK, and PI3K/mTOR." (PMID 31905951, 2019). "In sarcoma, IGF1R activation is known to activate the phosphatidylinositol-3-kinase/serine/threonine kinase Akt/Mammalian target of rapamycin (PI3K/Akt/mTOR) pathway which promotes cancer progression and metastasis." (PMID 28191313, 2017). "The present work provides proof-of-concept data on the pro-tumoral role of post-surgery fluids from GCTB in primary GCTB stromal cells, established sarcoma cell lines and mouse model in influencing stem cell growth and AKT/mTOR pathway activation." (PMID 29156702, 2017). "We therefore retrospectively evaluated the safety and efficacy of pazopanib combined with an inhibitor of HDAC, mTOR, Her2, or MEK in patients with advanced and refractory sarcoma enrolled in phase 1 trials of these combinations." (PMID 29162825, 2017). "Here, we report that the mTOR inhibitors rapamycin (sirolimus) and structurally related temsirolimus are capable of inducing UPR in sarcoma cells." (PMID 28926611, 2017). "In conclusion, this retrospective analysis of 100 sarcoma patients treated on phase I trials predominantly involving inhibitors of VEGF and/or mTOR demonstrated a clinical benefit rate of 36%." (PMID 27748430, 2016). "In a heterogeneous group of sarcoma patients, a combination of an IGF1R antibody and mTOR inhibitor has been shown to have clinical activity but the level of IGF1R expression was not predictive for response." (PMID 27418340, 2016). "Such dual targeted approaches targeting mTOR and Akt, or mTOR and PI3K have proven to be pertinent in preclinical models and one (targeting mTOR and IGFR-1) has reached the clinical phase in patients with advanced sarcomas and other solid tumors." (PMID 22761648, 2012). "Here, we use this model to test the response of primary mouse sarcomas to doxorubicin and to inhibition of the PI3K pathway with BKM120 (PI3K inhibitor) and BEZ235 (dual inhibitor of PI3K and mTOR), both provided by Novartis." (PMID 22619567, 2012). "Several inhibitors of mTOR are in clinical trials, including AP23573, which is being tested on metastatic sarcomas and other tumors." (PMID 22709827, 2012). "Dual PI3K/mTOR inhibitors can sensitize a variety of cancer cell lines to the treatment with DOX, but only one study reports combined treatment effects in sarcoma." (PMID 23300809, 2012).
sarcoma (continued). "Interestingly, sarcoma cells exposed to 400 μM PA promoted cell proliferation and activated the AKT/mTOR/S6 pathway through the phosphorylation of PTEN at T366." (PMID 38786008, 2024). "The IGF‐1R/mTOR pathway is the most common abnormal activation of the growth factor signaling cascade, and IGF‐1 regulates osteogenesis and homeostasis, which plays an important role in the pathogenesis of sarcoma." (PMID 36807772, 2023). "Growth factor receptors (GFR) activation spark different pathways, such as RAS/MAPK and PI3K/AKT/mTOR, activity and turn on transcriptional regulators, such as JUN/FOS/EGR1, that drive cell division, promote sarcoma cell proliferation, tissue organization and trophicity, and boost sarcomagenesis." (PMID 36232732, 2022). "In addition, we identify and validate important downstream target pathways commonly dysregulated in other translocation-positive sarcomas, including PRC2, mTOR, and TGFB." (PMID 32345977, 2020). "Exposure of sarcoma cells to neratinib, [pazopanib + entinostat], or the three-drug combination enhanced YAP and TAZ phosphorylation in parallel to a profound inactivation of mTOR resulting in phosphorylation of gate-keeper protein ATG13 S318." (PMID 31380285, 2019). "The rat sarcoma (RAS)/ERK and phosphatidylinositol-4,5-bisphosphate 3-kinase (PI3K)/mTOR pathways are two main signaling pathways controlling cell survival and proliferation which do not run side by side, but rather regulate each other by cross-inhibition or activation." (PMID 31430957, 2019). "The fact mTOR inhibitor ridaforolimus failed to be approved after the randomized clinical trials for all sarcomas, though that the drug responses to a particularly effective subtype (PEComa) was an also lesson." (PMID 29510588, 2018). "The total levels of mTORC1 components mTOR, Raptor and mLST8 in cell lysates were not altered in IS treated sarcoma cells." (PMID 27056897, 2016). "Although these are the first in-human results of this treatment for sarcomas, the numbers are too small to rule out the role of mTOR inhibitors as therapeutic agents, in particular for MPNSTs." (PMID 25810463, 2015). "In all cases these patients had a sarcoma subtype or connective tissue tumor with no other standard option (AF, angiosarcoma, chordoma...), and were treated with imatinib, sorafenib, or mTOR inhibitors." (PMID 25420707, 2014). "Indeed, combination of metformin with BEZ235, a dual mTOR and PI3K inhibitor gave synergistic results in all the three sarcoma histotype (CI<0.9)." (PMID 24391834, 2013). "Unfortunately, there is no proven clinical biomarker to predict the activity of mTOR inhibitors against sarcomas." (PMID 24216984, 2013). "mTOR inhibitors are not formally approved for treatment of sarcomas." (PMID 38469238, 2024). "KLF4 is a tumor suppressor gene, and mTOR is a proto-oncogene, so we speculate that overexpressed mTOR is not conducive to the prognosis of patients with sarcoma; the effect of KLF4 should be just the opposite." (PMID 34696664, 2022). "Treatment of HT1080 and MES sarcoma cells with axitinib and HDAC inhibitors reduced the expression of multiple HDAC proteins, an effect that was blocked by expression of an activated form of mTOR, previously shown by ourselves and others to prevent autophagosome formation." (PMID 34604061, 2021). "Downstream signaling cascades include the rat sarcoma/rat sarcoma-activated factor/mitogen activated protein kinase/extracellular regulated kinase kinase (Ras/Raf/MEK/ERK) and the phosphatidyl-inositide 3 kinase/protein kinase B/mammalian target of rapamycin (PI3K/AKT/mTOR) pathways." (PMID 27669229, 2016). "Thus, the combination of the mTOR inhibitor temsirolimus with doxorubicin is safe for heavily pretreated sarcoma patients, and the doxorubicin did not affect the pharmacokinetics of temsirolimus, but it does appear to have increased the exposure to its active metabolite." (PMID 33652741, 2021).
sarcoma (continued). "Moreover, recent preclinical studies indicated that HDACi can raise NK cell action against sarcoma cells, and that HDACi combined with PI3K/mTOR inhibitor, DNMT inhibitor or proteasome inhibitor may also represent a successful treatment option for sarcoma patients." (PMID 32532153, 2020). "The term “sarcomas” encompasses more than 50 different malignancies with differing molecular biology, clinical behaviour, responsiveness to treatment, and prognosis, and there is no current evidence that inhibition of the mTOR pathway is an active therapeutic strategy in low grade ESS." (PMID 25104960, 2014). "The reduction of immunosuppression is a useful therapeutic approach of post-transplantation KS; the introduction of an mTOR inhibitor may permit the remission of the sarcoma; however, the total regression of the lesions should not be the goal because of the risk of graft rejection." (PMID 23320218, 2012). "No discernable difference in mTOR pathway activation was identified between EWSR1-ETS and CIC-DUX4 positive sarcomas (EWSR1-ETS vs. CIC-DUX4: z-score = −0.2, p = 0.01)." (PMID 34021224, 2021). "Previous studies reported that induction of G1 arrest, but not apoptosis, following treatment of U-87MG, PC3M and sarcoma cell lines with BEZ235, the PI3K inhibitor ZSTK474, or the PI3K/mTOR inhibitor PI103." (PMID 29296217, 2017). "Similarly, IS did not disrupt the co-localization of mTOR and LTR in sarcoma cells." (PMID 27056897, 2016).